DDR1 (discoidin domain receptor tyrosine kinase 1)
Diseases named in the same sentence as DDR1 in open-access papers (continued):
Sharing a sentence is not in itself a finding about the gene and the disease.
psychosis (1 paper, 2023). "In patients with early psychosis, NLR was associated with a leukocyte discoidin domain receptors (DDR1) hypermethylation, which was increased in patients compared to healthy controls." (PMID 36830666, 2023).
pulmonary TB (1 paper, 2024). "Whether Ddr1 (mouse) or DDR1 (human) gene polymorphisms contribute to pulmonary TB, or whether it could be a target for anti-fibrotic therapy in TB are areas open for investigation." (PMID 38861581, 2024).
renal carcinoma (1 paper, 2021). A carcinoma arising from the epithelium of the renal parenchyma or the renal pelvis. "In renal cancer OS-RC-2 and ACHN cell lines, collagen-mediated activation of DDR1 leads to increased expression of mesenchymal markers (vimentin/N-cadherin) and decreased expression of epithelial markers (E-cadherin)." (PMID 33917302, 2021).
rhabdomyosarcoma (1 paper, 2022). A rare aggressive malignant mesenchymal neoplasm arising from skeletal muscle. "Altogether, these results indicate that dense microfibrillar collagen‐rich microenvironments are detrimental to rhabdomyosarcoma cells through an apoptotic response orchestrated by the induction of DDR1 signaling and mechanical confinement." (PMID 35957513, 2022). "By developing and using collagen matrices with distinct stiffness and in vivo‐like microarchitectures, this study uncovers that the activation of DDR1 has pro‐apoptotic and of integrin β1 pro‐survival function, specifically in 3D rhabdomyosarcoma cell cultures." (PMID 35957513, 2022).
secondary hyperparathyroidism (1 paper, 2022). Overproduction of parathyroid hormone in response to influence external to the parathyroid glands. "The results of a clinical trial also showed a low to normal level of bone markers after treatment with nilotinib, despite secondary hyperparathyroidism, further revealing the antiresorptive effect of DDR1 inhibition." (PMID 36140274, 2022).
solitary fibrous tumor (1 paper, 2024). Solitary fibrous tumor (SFT) represents a diverse group of ubiquitous rare spindle cell neoplasms that may be benign or malignant and that most frequently arises from the pleura and peritoneum and rarely from other sites such as head and neck, liver and skeletal muscle. "Overexpression of IGF2 related to LOI and receptor tyrosine kinase genes including DDR1, ERBB2, and FGFR1 have implicated the IGF2-INSR pathway in sphere formation of solitary fibrous tumor (SFT)." (PMID 38812777, 2024).
steatosis (1 paper, 2020). Increased lipid within the cytoplasm of cells. "Consistent with reduced body weight and adiposity, hepatic steatosis was evident in Ddr1+/+ mice fed an HFD, while minimal lipid was detected in Ddr1−/− mice." (PMID 32360427, 2020).
synovial sarcoma (1 paper, 2021). "DDR1 has also been shown to be expressed in four synovial sarcoma cell lines SYO-1, HS-SY-II, YaFuSS and 1273/99 but silencing of DDR1 expression with RNAi did not alter cell proliferation." (PMID 34957097, 2021).
ulcerative colitis (1 paper, 2025). An inflammatory bowel disease involving the mucosal surface of the large intestine and rectum. "In conclusion, compounds 39713a, 34346a, and 34419a show promise as potential DDR1 inhibitors for the treatment of ulcerative colitis." (PMID 39940867, 2025). "Molecular dynamics simulations indicated that these compounds could serve as novel DDR1 inhibitors, presenting new treatment options for ulcerative colitis in clinical settings." (PMID 39940867, 2025). "DDR1 has been identified as a potential target for treating ulcerative colitis." (PMID 39940867, 2025).
uterine carcinosarcoma (1 paper, 2023). A usually aggressive malignant neoplasm arising from the uterine corpus and less often the cervix. "Cox regression analysis revealed that high DDR1 expression was a risk factor for COAD patients, and KM analysis found that high DDR1 expression was associated with a poor prognosis in uterine carcinosarcoma (UCS) patients." (PMID 37031216, 2023).
tumor (215 papers, 2007 to 2026). "Meanwhile, DDR1 has been implicated in tumor cell dormancy across various experimental models by upregulating type III collagen via STAT1 activation." (PMID 41492134, 2026). "Loss of Kindlin-3 disrupts DDR1/intβ1 interactions and leads to reduced adhesion and enhanced tumor progression." (PMID 41492134, 2026). "This suggests that higher DDR1 expression is associated with a reduced presence of immune cells in the tumor microenvironment." (PMID 40869052, 2025). "To address this gap, we performed a systematic pan-cancer analysis that interrogated DDR1’s diagnostic and prognostic value, genetic alterations, pathway associations, and immunotherapeutic relevance across multiple tumor types." (PMID 40869052, 2025). "Meta‐analysis revealed that DDR1 expression was tightly linked to collagen VI expression, which we showed was intimately associated with DDR1‐expressing tumour cells in tumour biopsies." (PMID 40401507, 2025). "Discoidin domain receptor 1 (DDR1) is a collagen-binding kinase that is implicated in tumor progression and immune escape, but its role in NSCLC is unclear." (PMID 41394854, 2025). "Functional CRISPR screens also support DDR1 as a negative regulator of antitumor immunity, revealing that DDR1 loss increases tumor susceptibility to cytotoxic T lymphocyte and NK cell killing." (PMID 40869052, 2025). "Stable knockdown of DDR1 by two specific shRNAs caused retarded growth of NUGC3 xenograft tumor (measured as the ratio of bioluminescence increase over time zero)." (PMID 40456688, 2025). "Elevated or mutated DDR1 expression has been observed in various cancer cell lines and primary tumor tissues, including those from the lung, pancreas, prostate, breast, brain, ovary, and liver." (PMID 40713963, 2025). "Elevated DDR1 expression was linked to advanced tumor stage (T3), older age (>65), female sex, and shorter progression-free survival, highlighting its prognostic relevance." (PMID 41394854, 2025). "Our analysis revealed PDAC as among the strongest examples of DDR1-associated immune exclusion, aligning with the tumor type’s known immune-desert phenotype." (PMID 40869052, 2025). "Single-cell heterogeneity analysis revealed that DDR1 was enriched in tumor-associated macrophages and neutrophils." (PMID 41394854, 2025). "Both stress relaxation and Young's modulus were reduced in Ddr1‐KD group, indicating decreased tumor stiffness associated with weakened collagen caused by DDR1 knockdown." (PMID 38953306, 2024). "For instance, the DDR1 or DDR2 activation mediated by collagen positively regulates the metastatic process involving tumor-associated neutrophils (TANs) and CAFs." (PMID 39769286, 2024). "When the H-score of DDR1 and β-catenin expression in carcinoma was correlated with clinicopathological parameters, it showed a significant association with the tumor (T) stage (P = 0.017)." (PMID 37271822, 2023). "DDR1 is directly associated with tumor cell immune escape in TNBC, and with fibrosis and collagen synthesis." (PMID 36382024, 2022). "High DDR1 immunostaining score was significantly associated, on univariate analysis, with male sex, left tumor location, BRAF wild type status, KRAS mutated status, and Annexin A10 negativity." (PMID 35205677, 2022). "Crossing DDR1−/− and MMTV-PyMT mice revealed that a loss of DDR1 expression increases the level of vimentin in the primary tumor while E-cadherin expression decreases." (PMID 33917302, 2021). "Conversely, within the same tumor we observed that regions of low DDR1 expression were associated with decreased CXCL5 expression (red arrow)." (PMID 34237033, 2021). "The inverse correlation of mir-199a-5p with DDR1 was also validated in stage III Indian HGSOC tumor samples with normal ovarian tissue where DDR1 gain with miR-199a-5p loss was observed." (PMID 34837026, 2021).
tumor (continued). "DDR1 is associated with tumor progression and is linked to regulating cell adhesion and migration via modulating the expression of MMPs like MMP1, MMP2, and MMP937,38." (PMID 34837026, 2021). "In the current study, we focus on DDR1 and 2 stromal components: collagen I and tumor-associated neutrophils." (PMID 34237033, 2021). "In the present study, we validated DDR1-associated collective cell invasion in OSCC tumor sections, and provided evidence that the small molecule inhibitor DDR1-IN-1 suppressed ALI in a mouse model with statistical significance." (PMID 32244515, 2020). "Upon activation by binding to collagen, DDR1 exhibits sustained receptor phosphorylation and induces several downstream signaling pathways linked to tumor progression in several human cancers." (PMID 31116512, 2019). "Prolonged activation of DDR1 is known to upregulate MMPs and MMPs are associated with the invasive and metastatic potential of tumor cells by their ability to degrade extracellular matrix (ECM)." (PMID 25369402, 2014). "Loss of DDR1 inhibited tumor cell proliferation, migration and invasion in vitro in numerous tumor cell lines." (PMID 25369402, 2014). "Several recent studies have examined the molecular mechanisms underlying the role of DDR1 in tumor progression, invasion, and metastasis." (PMID 21541037, 2011). "High tumor DDR1 expression was significantly associated with a poor outcome for disease-free survival (p = 0.032)." (PMID 21541037, 2011). "We were able to show that DDR1 expression is associated with the tumor grade and clinical disease stage, and is inversely correlated with the survival outcome of patients." (PMID 21541037, 2011). "An additional 23 matched tumour and normal tissues were tested for differential expression of DDR1 and DDR2, and previously reported somatic mutations." (PMID 17299390, 2007). "Additionally, DDR1 expression positively correlates with immunosuppressive cell populations, such as MDSCs and M2-polarized tumor-associated macrophages (TAMs), highlighting its involvement in fostering an immune-suppressive microenvironment." (PMID 40869052, 2025). "To mitigate potential bias and ensure comprehensive coverage of tumor types potentially associated with DDR1 upregulation, we compiled the union of cancer types identified as DDR1-high across the three databases for downstream analyses, including survival and immune correlation studies." (PMID 40869052, 2025). "Collectively, these data indicate that elevated epithelial DDR1 is accompanied by a quantitative loss and functional impairment of tumor-infiltrating cytotoxic T cells, thereby supporting a model in which DDR1-driven matrix remodeling contributes to immune evasion in PDAC." (PMID 40869052, 2025). "Recent studies of DDR1 have shown that its loss plays a role in the epithelial to mesenchymal transition and that higher levels of DDR1 expression decreases the invasive capacity of a tumor." (PMID 40614729, 2025). "Discoidin domain receptor 1 (DDR1), a collagen-binding receptor tyrosine kinase encoded on chromosome 6p21.3, promotes tumor progression and immune exclusion by regulating cell motility, extracellular matrix remodeling, and collagen alignment that restricts immune cell infiltration." (PMID 41394854, 2025). "Notably, the association of DDR1 with 63 immunoregulatory genes underscores its central role in tumor immune regulation." (PMID 41394854, 2025). "Furthermore, DDR1 expression was significantly associated with microsatellite instability in 6 cancers and tumor mutation burden in 11 cancers." (PMID 37031216, 2023). "However, divergent results showed that DDR1 high mRNA expression was associated with worse OS whatever the tumor stage." (PMID 35205677, 2022).
tumor (continued). "Interestingly, this anti-tumor effect was associated with a diminution of drug-induced collagen remodeling, suggestive of a feedforward loop between DDR1/2 and collagens." (PMID 35936735, 2022). "In univariate analysis, a high DDR1 immunostaining score was significantly associated with male sex (p = 0.0195), left tumor location (p = 0.0114), BRAF wild-type status (p < 0.0001), KRAS mutated status (p = 0.0041), and absence of expression of the serrated markers Annexin A10 (p = 0.0097)." (PMID 35205677, 2022). "Lastly, DDR1 can associate with TM4SF1 to induce metastatic tumor colonization." (PMID 33917302, 2021). "DDR1 is associated with tumor progression, invasion, and drug resistance." (PMID 34837026, 2021). "DDR1 is an atypical collagen receptor linked to tumor progression, but whether SCs express DDR1 and its implication in liver metastasis remain unknown." (PMID 33110221, 2020). "Positive expression of DDR1 was associated with tumor invasion (P = 0.017)." (PMID 28143619, 2017). "In addition, multivariate logistic regression analysis identified high DDR1 expression as the single independent factor associated with advanced tumor stage, and, hence, poor prognosis." (PMID 20799954, 2010). "Increased DDR1 expression in HCC was associated with advanced tumor stage." (PMID 20799954, 2010). "The loss of DDR1 expression in tumors might contribute towards attenuated tumor growth." (PMID 25369402, 2014). "Both genetic and pharmacological inhibition of DDR1 disrupts this complex, enhancing ferroptosis, increasing tumor immunogenicity, and promoting CD8+ T cell infiltration, with the amplification of the antitumor efficacy of carbon ion radiotherapy." (PMID 41492134, 2026). "Discoidin Domain Receptor 1 (DDR1), a collagen receptor with tyrosine kinase activity, has garnered attention as a regulator of tumor-stroma interactions and immune evasion." (PMID 40993737, 2025). "Combining the DDR1 blockade with gemcitabine produced striking therapeutic synergy, resulting in maximal tumor growth suppression and pronounced inflammatory infiltration." (PMID 40869052, 2025). "Collectively, these findings emphasize DDR1’s critical regulatory role in shaping the tumor immune microenvironment and support its potential application as a biomarker and therapeutic target in immunotherapy." (PMID 40869052, 2025). "Immunohistochemistry showed that CENPE protein levels were reduced in the tumour cells of DDR1‐positive cases of DLBCL." (PMID 40401507, 2025). "Differential expression analysis of DDR1 in different subgroups of the TCGA dataset revealed that DDR1 expression was significantly higher in tumor samples than in control samples (Tumor: 7.06 ± 0.968 vs. Normal 5.95 ± 0.465, P < 0.05)." (PMID 41394854, 2025). "During this process, collagen-mediated DDR1 activation induces PYK2-associated signaling pathways, potentially driving collagen-induced tumor progression." (PMID 40746536, 2025). "Subsequent correlation analysis revealed a significant positive correlation between DDR1 expression levels and tumor proliferation signature scores in TCGA GC patients." (PMID 40456688, 2025). "DDR1 expressed on tumor cells modulates collagen fiber arrangement and manipulates microenvironmental immunity." (PMID 40025071, 2025). "Another DDR1 inhibitor, sitravatinib, induces tumor immune landscape changes that enhance the efficacy of immune checkpoint blockade in refractory cancer models." (PMID 40603853, 2025). "Orthotopic or spontaneous tumor models, and eventually clinical trials, are needed to validate that DDR1 blockade effectively remodels collagen and enhances immune infiltration within an appropriate physiological context." (PMID 40869052, 2025). "Collectively, these findings establish that USP7 deubiquitinates and stabilizes DDR1, and that USP7 inhibition promotes DDR1 ubiquitination and degradation, ultimately suppressing tumor cell proliferation both in vitro and in vivo." (PMID 40713963, 2025).
tumor (continued). "DDR1 controls tumor cell proliferation and metabolism, and DDR1 expression level correlates with patient survival and response to therapy." (PMID 40025071, 2025). "Together with the extensive tumor necrosis and pronounced inflammatory infiltrates, these findings show that the combined inhibition of DDR1 and chemotherapy produces the most potent antitumor effect, likely through an augmented immune-mediated response." (PMID 40869052, 2025). "Third, given that DDR1 knockdown attenuated tumor invasion and migration, our focus on survival/proliferation mechanisms warrants expanded investigations into DDR1’s role in metastatic regulation." (PMID 40993737, 2025). "Clarifying these points would strengthen evidence that DDR1 inhibition broadly reshapes the tumor immune landscape beyond T cell infiltration." (PMID 40869052, 2025). "The concurrent enrichment of ECM-remodeling pathways further suggests that stromal disruption by DDR1 blockade facilitates immune cell infiltration and tumor clearance." (PMID 40869052, 2025). "Our integrative analysis identifies DDR1 as a critical regulator of the immune-excluded tumor microenvironment across multiple cancers." (PMID 40869052, 2025). "For instance, collagen glycosylation can regulate the interact site between tumor cells and type I collagen, inhibiting the activation of the DDR1 site and thereby affecting tumor cell proliferation." (PMID 41141851, 2025). "This is achieved, in particular, by binding of the discoidin domain receptor 1 (DDR1), a collagen receptor with tyrosine kinase activity, of tumor cells to the fibrillar collagen of the TME." (PMID 40519272, 2025). "DDR1 appears to drive tumor progression and immune evasion through its pivotal roles in extracellular matrix remodeling and modulation of immune signaling pathways." (PMID 40869052, 2025). "DDRs are located primarily on the surface of tumor cells and represent a unique class of receptor tyrosine kinases (RTKs) that can bind to collagen fibers and sense mechanical forces, mainly DDR1 and DDR2." (PMID 39799341, 2025). "The present study identifies DDR1 as a potential drug target and tumor biomarker through an iTRAQ-based phosphoproteomic screen." (PMID 40456688, 2025). "To further clarify the mechanism by which DDR1 regulates ferroptosis in BC cells, we performed RNA‐seq on TCCSUP cells and HOXA6, a tumour‐associated gene." (PMID 40105492, 2025). "Future studies are needed to explore how DDR1 inhibition affects DNA repair processes and to determine if this pathway can enhance tumor sensitivity to chemotherapy." (PMID 40869052, 2025). "High DDR1 expression broadly correlated with reduced immune cell infiltration and lower immune/stromal scores, indicative of an immunosuppressive tumor niche." (PMID 40869052, 2025). "Tumor immune cycle analysis revealed significant differences in 16 steps between the high and low DDR1 expression groups of NSCLC patients (P < 0.05), with higher proliferation levels in the high-risk group." (PMID 41394854, 2025). "Examination of the matched samples (i.e., normal and tumor tissues from the same patients) showed that > 50% of the cases had DDR1 upregulated in tumor tissues compared with matched normal tissues, suggesting that DDR1 is required for cancer development." (PMID 40456688, 2025). "Comparative studies have shown that this compound is significantly more effective in inhibiting tumor progression than the DDR1 inhibitor 7 rh." (PMID 40563472, 2025). "Based on this, a highly selective DDR1 inhibitor 7rh was employed to investigate its ability to sensitize tumor cells to CIR." (PMID 40993737, 2025). "Cancer cell phenotype plasticity is critical for tumor progression, and DDR1 plays a significant role in this process." (PMID 40563472, 2025).